TLR4 (toll like receptor 4)
Diseases named in the same sentence as TLR4 in open-access papers (continued):
Sharing a sentence is not in itself a finding about the gene and the disease.
periodontitis (continued). "Regarding TLR4 1196 C>T polymorphism, the T allele was associated with an increased risk of developing periodontitis in Caucasians in an additive model of inheritance." (PMID 31281226, 2019). "In parallel, polymorphisms of TLR-4 and its co-receptor (CD 14) have been found to be related to periodontitis." (PMID 28210435, 2017). "Although we can not preclude other effects, which reduced the alveolar bone loss, the attempt to block the TLR4 or NF-κB pathway to treat periodontitis shows encouraging results." (PMID 24887697, 2014). "Blocking TLR4 or NF-κB signaling partially reversed the decreased osteogenic potential of PDLSCs and prevented the alveolar bone loss caused by LPS experimental periodontitis in rats." (PMID 24887697, 2014). "In the periodontium, TLR4 is expressed by epithelial cells, fibroblasts, and periodontal ligament stem cells, and its overactivation has been implicated in tissue breakdown and alveolar bone resorption during chronic periodontitis." (PMID 41002387, 2025). "In order to understand how periodontal diseases begin and develop, it is essential to know and characterize the bacterial profiles present in our population and the frequency of the A-2570G, A896G, and C1196T polymorphisms of the TLR4 gene and their association with periodontitis." (PMID 40552316, 2025). "Toll-like receptors (TLR2 and TLR4) are crucial in the detection of pathogen-associated molecular patterns (PAMPs) during periodontitis, resulting in exacerbated production of proinflammatory cytokines and ultimately tissue damage and bone loss associated with this periodontal disease." (PMID 40371381, 2025). "However, the AAAGCC haplogenotype had a 2.3 times higher risk of developing periodontitis; both genotypes can occur in polymorphic heterozygous individuals for SNP A-2570G of the TLR4 gene." (PMID 40552316, 2025). "Therefore, evaluating the association between the TLR-4 polymorphisms and subgingival microbiota in patients with periodontitis is necessary." (PMID 40552316, 2025). "Our findings indicated that inhibition of P.g-OMVs release and targeting SAA3-mediated TLR4/MyD88/NF-κB axis could be possible strategies to rescue periodontitis-induced alveolar bone loss." (PMID 40791819, 2025). "Our study suggests that targeting P.g-OMVs release or SAA3/TLR4/MyD88/NF-κB axis may be an effective strategy to rescue periodontitis-induced alveolar bone loss." (PMID 40791819, 2025). "Several lines of evidence have recently documented that TLR4 could inhibit the osteogenic differentiation of PDLCs and PDLSCs, which might further aggravate Pg‐LPS‐induced periodontitis and alveolar bone loss." (PMID 38318762, 2024). "The results showed that patients with chronic periodontitis who harbored the AG polymorphism of TLR4 rs1927907 were significantly more likely to develop COPD complications than patients with the GG genotype (OR, 1.94) after adjusting for age, sex, smoking, and oral hygiene habits." (PMID 37762876, 2023). "Some scholars performing a meta-analysis of the susceptibility of TLR4 polymorphism to periodontitis revealed that TLR4 C>G (rs7873784) may be associated with CP in the Asian population and be transmitted to the next generation in a recessive form." (PMID 31380305, 2019). "Additionally, TLR4 polymorphisms are associated with various inflammatory diseases such as aortic aneurysmal disease, periodontitis, psoriasis arthritis, and Crohn’s disease." (PMID 30877182, 2019). "Therefore, ablating TLR2 or TLR4 signaling, modifies differentially the susceptibility to develop periodontitis and dependent on mouse strain." (PMID 29163477, 2017). "Bacteroides thetaiotaomicron which promotes intestinal health produces TLR4-stimulatory lipid A which has a 1-phosphate while P. gingivalis which is associated with the chronic oral inflammatory disease periodontitis produces TLR4-evasive lipid A containing a 4′-phosphate component." (PMID 29018490, 2017).
periodontitis (continued). "In addition, the extent of periodontitis based on the amount of alveolar bone loss is less in TLR4 LOF animals compared to that of wild type (WT)." (PMID 26317345, 2015). "We hypothesized that blockage of TLR4 or NF-κB would also prevent alveolar bone loss in LPS induced experimental periodontitis." (PMID 24887697, 2014). "Blocking the TLR4 or NF-κB pathway partially reversed the impaired osteogenic potential of PDLSCs after LPS treatment and prevented the alveolar bone loss induced by LPS in experimental periodontitis in rats." (PMID 24887697, 2014). "The data are consistent with the interpretation that activation of TLR4 by this mechanism may contribute to systemic inflammation that has been observed in periodontitis, and may contribute to the observed associations between periodontal and systemic inflammatory conditions." (PMID 30192824, 2018). "The primary objective of this study was to test the hypothesis that periodontitis can cause prediabetes (GI and IR) and the primary pathway that leads to GI/IR is dependent on the phenotype of TLR4 expressed by the resident cells in the liver, primarily Kupffer cells." (PMID 26317345, 2015). "We have also shown that periodontitis induced by placement of LPS soaked ligatures around molar teeth impairs hepatic insulin signaling via TLR4 and this impairment is reduced in mice with whole body TLR4 loss of function (LOF) in animals fed a high fat (HF) diet." (PMID 26317345, 2015). "In addition, blockage of TLR4 or NF-κB signaling prevented the alveolar bone loss caused by LPS, which may provide a new clue for periodontitis therapy." (PMID 24887697, 2014). "The expression of TLR-4 was significantly elevated (p < 0.05) by 127.66 (±20.94)% in the periodontitis-induced control group relative to the normal group." (PMID 41614939, 2026). "The non-synonymous Asp299Gly (rs4986790) and Thr399Ile (rs4986791) variants, which are uncommon in non-European groups but relatively common in Europeans, have been the subject of the majority of genetic research on TLR4 and periodontitis." (PMID 41002387, 2025). "Our previous studies have demonstrated alterations in neuroinflammation, such as TLR‐4 and S1P pathways, in the FC of rats exposed to a combined protocol of periodontitis and CMS." (PMID 41326981, 2025). "In this study, IHC assays further demonstrated that P. gingivalis increased Tlr2, Tlr4 and Myd88 expression in P. gingivalis-induced mouse periodontitis compared with that in the controls." (PMID 40307566, 2025). "Recent studies have confirmed that DERL3 participates in the pathogenesis of periodontitis by modulating the TLR4/MyD88 pathway through KAT3B-regulated succinylation modification." (PMID 41459503, 2025). "Given the overlapping inflammatory pathways in ESRD and periodontitis and the central role of TLR4 in microbial sensing, the rs2149356 SNP offers a biologically plausible link between genetic predisposition and host–microbe interactions." (PMID 41002387, 2025). "The data unequivocally demonstrates that in a model of periodontitis induced by high sugar consumption, the activation of TLR4 and subsequent engagement of the downstream factor NF-κB signaling cascade are prominently observed." (PMID 40173189, 2025). "PTCSC3 is a regulatory molecule that potentially modifies inflammatory responses in periodontitis by downregulating TLR4." (PMID 39063437, 2024). "Five hub ICD-related genes (ENTPD1, TLR4, LY96, PRF1 and P2RX7) were identified for the construction of a diagnostic model for periodontitis." (PMID 39555084, 2024). "Some studies have demonstrated the involvement of TLR2 and TLR4 in the pathogenesis of oral diseases, such as chronic periodontitis and dental caries." (PMID 39000094, 2024). "LPS levels are higher in periodontitis sites compared to healthy sites in subgingival plaques, as measured using a TLR4-based method." (PMID 39770870, 2024).
periodontitis (continued). "NAC‐S2 ameliorate inflammation mediated by TLR4/NF‐κB pathway in mouse chronic periodontitis models." (PMID 37647428, 2023). "We mainly discovered that the expression of circ_0099630 and TLR4 was elevated in periodontitis patients and LPS-treated HPDLCs." (PMID 38007427, 2023). "TLR2-/-, TLR4-/-, TLR2&4-/-, and TLR9-/- mice exhibited the reduced alveolar bone loss in various mouse periodontitis models, suggesting that TLRs indeed played an important role in developing discordant oral barrier immunity." (PMID 38015204, 2023). "In the periodontitis group, macrophages were observed to exhibit elevated expressions of TLR4, IFNAR1 (the receptor of IFNβ), ISG15, ITGB2 (the receptor of ISG15), IL10." (PMID 37876725, 2023). "In this study, we constructed cell membrane-coated silk fibroin nanoparticles (MSNCs) overexpressing TLR4 by genetic engineering and proposed a new antibacterial and immunoregulatory synergistic therapy for periodontitis." (PMID 36761293, 2023). "In the progression of periodontitis in human, NF-κB can be activated by LPS-induced Toll-like receptor 4 (TLR4) activation, which activates gene expression of multiple proinflammatory cytokines, such as IL-1, IL-6, and TNF-α." (PMID 36846719, 2023). "TLR4, as the predominant bacterial endotoxin receptor that recognizes innate immunity, plays a vital role in the activation of the immune response in periodontitis." (PMID 36761293, 2023). "The expression of circ_0099630 and TLR4 was elevated in periodontitis patients and LPS-treated HPDLCs." (PMID 38007427, 2023). "The expression of TLR4 was also elevated in the experimental periodontitis rat, and Baicalin played anti-inflammatory effects in periodontitis rat by depleting the expression of TLR4." (PMID 38007427, 2023). "Genotyping of six candidate SNPs in TLR4 was performed in 339 patients with chronic periodontitis only and in 373 patients with chronic periodontitis and COPD." (PMID 37762876, 2023). "When using TLR4‐/‐ or Myd88‐/‐ mice to establish the periodontitis model, we find that CEJ to ABC distance is much lower than that of WT mice." (PMID 37647428, 2023). "The aberrant expression of circ_0099630 and TLR4 hinted that they were involved in periodontitis development." (PMID 38007427, 2023). "Collectively, circ_0099630 and TLR4 were highly expressed in periodontitis patients and LPS-treated HPDLCs." (PMID 38007427, 2023). "All of these results indicate that NAC‐S2 ameliorates TLR4/NF‐κB pathway mediated inflammation in mouse periodontitis model." (PMID 37647428, 2023). "A periodontitis mouse model was established by ligating the subgingival between the first and second molars in wild‐type, TLR4‐/‐, and Myd88‐/‐ mice." (PMID 37647428, 2023). "At last, we determined the effect of NAC‐S2 on periodontitis mouse models that were established in WT mice, TLR4‐/‐ mice, and Myd88‐/‐ mice." (PMID 37647428, 2023). "TLR4 was reported to be upregulated in chronic periodontitis, and the downregulation of TLR4 contributed to the inhibition of inflammation in periodontitis." (PMID 38007427, 2023). "In summary, this study demonstrates that NAC‐S2 inhibits various pro‐inflammatory cytokines and periodontitis in mouse model in TLR4/Myd88‐dependent manner." (PMID 37647428, 2023). "Some studies have found that TLR4 was closely related to the occurrence and development of some inflammatory oral diseases, such as recurrent aphthous ulcer and periodontitis." (PMID 35719331, 2022). "Elevated expression of toll-like receptor 2 and toll-like receptor 4 is found in gingival tissue biopsies from patients with DM and periodontitis compared with patients with periodontitis alone." (PMID 35694215, 2022). "Basic studies using TLR4 knockout mice models have documented that TLR4 is involved in periodontitis and peri-implantitis initiated by P. gingivalis." (PMID 36093182, 2022).
periodontitis (continued). "Toll-like receptor 4 (TLR4) is the most characterized pattern recognition receptor during periodontitis and has been largely argued for its crucial role in the LPS-mediated pyroptosis pathway." (PMID 36093182, 2022). "Similar findings were reported by De Oliveira and colleagues, observing trends for hypermethylation in TLR2 genes and significant hypomethylation of TLR4 gene profiles in periodontitis tissues compared with healthy samples." (PMID 36291079, 2022). "A previous study indicated that TLR4 can remarkably increase inflammatory responses in vivo, and inhibiting TLR4 can significantly improve the symptoms of periodontitis in mice." (PMID 33679417, 2021). "Both the expressions of circMAP3K11 and TLR4 were negatively correlated with the expressions of miR-511-3p in periodontitis." (PMID 33679417, 2021). "Afterward, immunohistochemistry and RT-PCR analyses were performed to investigate the expression of TLR4 in periodontal ligament tissue of periodontitis and normal patients." (PMID 33679417, 2021). "TLR4 expression in periodontal ligament tissue of periodontitis group was significantly higher than that of normal group." (PMID 33679417, 2021). "In the present study, we revealed that circMAP3K11 is involved in periodontitis development by regulating TLR4 expression by sponging miR-511-3p." (PMID 33679417, 2021). "Possible associations between SNPs in CD14 (rs2569190), NF-κB (rs28362491), TLR2 (rs5743708), and TLR4 (rs4986790) and the occurrence of severe periodontitis were investigated in the cohort of CV patients." (PMID 34305452, 2021). "Recently, it was reported that the upregulation of TLR4 inhibits the osteogenic differentiation of PDLSCs in an inflammatory environment, suggesting the important role of TLR4 for regenerative capacity of PDLSCs in periodontitis." (PMID 33679417, 2021). "The hPDLSCs isolated from periodontitis patients were used as a cell model of inflammatory microenvironment to study the effect of the circMAP3K11/miR-511-3p/TLR4 axis on the proliferation, apoptosis and migration of hPDLSCs under inflammatory conditions." (PMID 33679417, 2021). "Taken together, our study preliminarily uncovered a circMAP3K11/miR-511-3p/TLR4 axis that regulates the function of hPDLSCs in periodontitis, providing novel insight and scientific base in the treatment of periodontal tissue regeneration based on stem cells." (PMID 33679417, 2021). "As reported, TLR4 is capable of mediating the activation of proinflammatory cytokines and worsening periodontitis." (PMID 33679417, 2021). "The results hinted that targeting circMAP3K11/miR-511-3p/TLR4 axis is a feasible strategy for periodontitis therapy, providing novel insights in the treatment of periodontal tissue regeneration based on stem cells." (PMID 33679417, 2021). "Consistently, distinct TLR2 and TLR4 promoter methylation patterns have been reported in periodontitis and Behçet's disease." (PMID 34031466, 2021). "Based on this, we sought to explore the roles of circMAP3K11/miR-511/TLR4 axis for regenerative capacity of PDLSCs under inflammatory conditions to uncover the molecular mechanisms governing periodontitis pathogenesis." (PMID 33679417, 2021). "Nevertheless, the biological function of circMAP3K11/miR-511-3p/TLR4 axis in periodontitis progression is in need of further investigation and the current study was a preliminary one to pave the way for further research in this field of science." (PMID 33679417, 2021). "Compared to the periodontal tissues from normal subjects, those from periodontitis patients exhibited higher expression levels of circMAP3K11 and TLR4, and lower expression level of miR-511-3p." (PMID 33679417, 2021). "Collectively, our study is the first to show that the expression of TLR4 in periodontitis is regulated by a circRNA and the first to report the mechanism and clinical significance of circMAP3K11 in periodontitis." (PMID 33679417, 2021).
periodontitis (continued). "TLR2 and TLR4 are essential signaling proteins in progression of inflammation and related bone metabolism in periodontitis." (PMID 32291538, 2020). "It has been shown that ligature and injection-induced periodontitis in mice is regulated through the activation of the TLR4 and TLR2 receptors." (PMID 32793243, 2020). "When the rmlC/rmlC+ complemented strain was used for the periodontitis induction, the expression of Tlr4 reached similar levels to the ones detected in the VT1169 wild-type strain-induced periodontitis lesions." (PMID 33193431, 2020). "Clinical studies have demonstrated that the levels of TLR2 and TLR4 in periodontitis patients were significantly higher than those in control groups." (PMID 32760399, 2020). "It has also been observed that anti-cardiolipin antibodies (aCL) from patients with periodontitis can be proinflammatory, promoting the activation of cell TLR4 pathways." (PMID 33363538, 2020). "TLR2 soluble in saliva shows an inverse correlation and TLR4 soluble directly with clinical parameters in periodontitis." (PMID 33363538, 2020). "Growing evidence indicated that TLR4-mediated NF-κB signaling plays an important role in the progression of periodontitis." (PMID 32735017, 2020). "Taken together, knockdown of TRIM52 mitigated LPS-induced inflammatory injury via the TLR4/NF-κB signaling pathway, providing an effective therapeutic target for periodontitis." (PMID 32735017, 2020). "TLR2 and TLR4 are the most extensively researched receptors of the TLR family in relation to periodontitis in mice and men." (PMID 32793243, 2020). "So far, a number of studies have evaluated the association between PRRs, SNPs, and periodontitis, including CD14, TLR2, TLR4, and MBL2." (PMID 32831974, 2020). "Previous DNA microarray study has shown an up-regulated expression of toll-like receptor 4 (TLR4) in periodontitis patients’ gingival fibroblasts as compared to healthy individuals." (PMID 33329037, 2020). "Several animal studies with different periodontitis models showed that TLR-2-deficient mice exhibit lower levels of alveolar bone loss and proinflammatory cytokine expression compared to wild-type and TLR-4-deficient mice." (PMID 32714091, 2020). "TLR2 and TLR4 are the most widely studied extracellular innate receptors that recognize various PAMPs and are likely to play a role in the pathogenesis of periodontitis." (PMID 33322059, 2020). "An activation of TLR4 observed in chronic periodontitis increases the production of proinflammatory cytokines." (PMID 31035477, 2019). "Our RNA-seq data showed that PTCSC3 was likely downregulated in periodontitis, and its expression levels were inversely correlated with toll-like receptor 4 (TLR4), which promotes periodontitis." (PMID 31196168, 2019). "In this study we found that PTCSC3 was downregulated, while toll-like receptor 4 (TLR4) was upregulated in periodontal ligament stem cells (PDLSCs) isolated from periodontitis affected teeth that in PDLSCs isolated from healthy teeth." (PMID 31196168, 2019). "TLR4 is usually highly expressed in periodontal ligament mesenchymal stem cells and activation of TLR4 can mediate immune recognition of periodontal pathogens, indicating its involvement in periodontitis." (PMID 31196168, 2019). "Consistent with previous studies, our study also showed the upregulation of TLR4 in periodontitis-affected PDLSCs." (PMID 31196168, 2019). "This study aimed to investigate the role of PTCSC3 in periodontitis and explored its interactions with TLR4 by performing overexpression experiments, which recovered the downregulation of PTCSC3." (PMID 31196168, 2019). "Expression of PTCSC3 and TLR4 mRNA in 34 cases of periodontitis-affected PDLSCs and 34 cases of healthy PDLSCs was detected by RT-qPCR." (PMID 31196168, 2019). "Although TLR2 and TLR4 have been shown to be important for the progression of inflammation and related bone metabolism in periodontitis, little is known about their contributions to the disease." (PMID 31281226, 2019).